APOE (apolipoprotein E)
Diseases named in the same sentence as APOE in open-access papers (continued):
Sharing a sentence is not in itself a finding about the gene and the disease.
hyperlipidemia (continued). "After feeding a western diet for 12 weeks, the ApoE–/– mice in the MOD group developed severe hyperlipidemia, as indicated by higher plasma levels of TC, TG, and LDL, as well as lower HDL, compared to CON mice." (PMID 31623159, 2019). "Herein, we investigated the in vivo anti-hyperlipidemia activity of simvastatin combined with lunasin in ApoE−/− mice fed an HFD." (PMID 31731717, 2019). "Although all of them showed hyperlipidemia, apoE was still detected in the plasma by Western blotting." (PMID 30885208, 2019). "The study suggests that a high-fat diet in ApoE-/- mice induces hyperlipidemia, rapid changes to crucial taxon in the gut microbiota, and significant differences in serum metabolite levels." (PMID 31269076, 2019). "In our study, we observed that the ApoE KO mice fed with high-fat diet for 8 weeks, showed a serious hyperlipidemia at 16 weeks of age." (PMID 30669336, 2019). "Considering that AS is induced by hyperlipidemia, we first tested the levels of serum lipids in ApoE−/− mice." (PMID 30713570, 2019). "In hyperlipidemia ApoE and CCR2 double knockout mice, there is a marked reduction in atherosclerotic plaque with no change in lipid measures compared to ApoE knockout mice." (PMID 30873416, 2019). "To gain insights in the mechanisms by which Irisin prevented hyperlipidemia in ApoE-/-mice, we analyzed the expression of genes involved in cholesterol metabolism." (PMID 31191305, 2019). "WD-fed ApoE−/− mice developed atherosclerotic plaques and hyperlipidemia along with obesity, which were significantly ameliorated by DCA administration." (PMID 31570705, 2019). "ApoE−/− mice show abnormal hyperlipidemia and exhibit systemic metabolic and functional abnormalities including arterial fat accumulation after 12 weeks of high-fat diet feeding." (PMID 31446617, 2019). "The effects of miR-26a on hyperlipidemia in apoE−/− mouse model were further explored by measuring the serum lipid levels of clinical atherogenic factors including TC, TG, LDL-C, and HDL-C." (PMID 29387339, 2018). "Remarkably, these protective effects persist even when apoE is present at sub-physiological levels that lead to hyperlipidemia." (PMID 29789495, 2018). "Of note, the mixed phenotype in diabetic ApoE−/− mice, characterized by hyperglycaemia and hyperlipidaemia, reflects the situation in diabetic patients, in which likewise both risk factors are increased." (PMID 30271984, 2018). "Periodontal tissues in ApoE−/− hyperlipidemia model rats are reported to exhibit more TRAP-positive multinuclear cells and increased TLR2 and TLR4 expression levels, suggesting that high oxLDL concentration effects osteoclastogenesis via the elevation of TLRs." (PMID 29859535, 2018). "In a previous study, we demonstrated that quercetin reduces hyperlipidaemia and lipid accumulation in the liver and aorta in the apoE−/− mice fed a high-fat diet." (PMID 28088205, 2017).
hyperlipidemia (continued). "Due to the knockout of apolipoprotein E in this animal mouse model, mice are very hyperlipidemia and a total regress of plaque burden cannot be expected." (PMID 28771481, 2017). "We used ApoE−/− mice to potentiate the effects of aberrant lipid signaling and exacerbate consequences of hyperlipidemia, which affects ApoB-containing lipoprotein particles originating from both intestine and liver." (PMID 28380440, 2017). "A recent study conducted in IVDs of an ApoE knockout mice model also suggested that hyperlipidemia can increase the expression of MMP3 and accelerate IVDD43." (PMID 28785062, 2017). "First, we confirmed that rebamipide decreased plaque formation in the aorta and improved hyperlipidemia in ApoE-KO mice." (PMID 28241014, 2017). "There is a close correlation between elevated APOE and hyperlipidemia in metabolic syndrome patients." (PMID 27853276, 2016). "Some studies found that the increased plasma apoE of apolipoproteins in aged hyperlipidemia rats can increase HDL after a long period." (PMID 26289078, 2015). "Our results demonstrate that apoE−/− mice given a HFD for 16 weeks present obvious hyperlipidemia and increased body weight, as compared to the control group." (PMID 24972137, 2014). "In accord with APOE E4 status, hyperlipidemia and eGFR were significantly higher in the E4 carriers." (PMID 25530658, 2014). "ApoE gene is upregulated/expressed in many organs and tissues in the gerbil and is highly expressed in the brain and kidney of gerbils with hyperlipidemia." (PMID 25006576, 2014). "Ang II-induced cardiac fibrosis was also exacerbated in ApoE−/−/IP−/− double knockout mice with hyperlipidemia." (PMID 24852754, 2014). "Our previous studies have demonstrated that high fat diet (Western diet) fed with ApoE KO mice for 8 weeks can induce more severe hyperlipidemia and lipid droplet accumulation in liver and heart." (PMID 23570453, 2013). "In conclusion, the present study reveals that hyperlipidemia induces inflammation, oxidative stress and accelerates renal damage in ApoE KO mice; and this is accompanied by down-regulation of Klotho expression." (PMID 24386260, 2013). "We used Masson staining to evaluate hyperlipidemia-mediated renal pathological change in ApoE KO mice." (PMID 23570453, 2013). "HC diet induced an increase in total cholesterol in both WT and ApoE KO mice, but hyperlipidemia was more pronounced in ApoE KO mice." (PMID 24386260, 2013). "Although we observed an inhibited innate immune response and TREM-1 expression in hyperlipidemic ApoE−/− mice, the possible mechanism by which hyperlipidemia influences PRRs has not been fully understood." (PMID 23977160, 2013). "Results of our study demonstrate that macrophages respond to diet-induced hyperlipidemia by raising plasma apoE levels and enriching remnant lipoproteins in apoE, thereby reducing plasma cholesterol levels." (PMID 22606237, 2012). "As expected for the apoE−/− mouse, which is a severe model of hyperlipidemia, plasma TC was elevated on the HFC diet, with typical elevations in VLDL-C in all dietary groups." (PMID 23285120, 2012). "We found that western diet-fed apoE-/- mice treated with either atorvastatin or rosuvastatin led to a substantial reduction in the CD68+ cell content in the plaques despite continued hyperlipidemia." (PMID 22163030, 2011). "Using intercrosses derived from apoE−/− mouse strains, we and others have identified distal chromosome 1 as a major region contributing to hyperlipidemia." (PMID 22022387, 2011). "The distributions of gender, hyperlipidemia, cardiovascular disease, and APOE e4 status were similar between VaD cases and controls." (PMID 21674003, 2011). "Our study showed that hyperlipidemia and the early and advanced stage of typical atherosclerotic lesions formed in apoE-/- mice fed with regular chow or a high-fat diet." (PMID 20040117, 2009).
hyperlipidemia (continued). "The expression and rhythmicity of circadian genes in hearts and livers of apoE-/- mice were altered by the hyperlipidemia." (PMID 20040117, 2009). "Moreover, comorbidity mouse models with hyperlipidemia and mIRI were prepared in ApoE−/− background mice." (PMID 39853712, 2025). "In contrast, in Taiwanese, Omani, Alaska Native and Afro-Caribbean populations, APOE ε4 only indirectly increases IHD risk through hyperlipidemia, but has no detectable independent contributions to IHD." (PMID 41282305, 2025). "We also detected five APOE variants previously associated with other hyperlipidemias but not with FD." (PMID 39684364, 2024). "In keeping with a link between cardiovascular health and apoE levels, this may explain why physical interventions seem to boost the effect of protein in the control of hyperlipidemia." (PMID 39234633, 2024). "We showed that the treatment of chow-diet-fed male APOE knockout mice with a standard oral dose of 10 mg/kg/day LXR agonist T0901317 was associated with hepatic fat accumulation, exacerbated hyperlipidemia, and monocytosis and stimulated early atherosclerotic lesion development." (PMID 38672446, 2024). "Additionally, the ApoE gene which is known to positively correlated to cardiovascular disease and hyperlipidemia is cell-specifically expressed and mainly expressed in the liver and other organs including the small intestine and brain in humans and mice." (PMID 39598239, 2024). "The results underscore the significance of APOE gene sequencing in patients with hyperlipidemia." (PMID 39684364, 2024). "In this work, we have used the ApoE−/− mice that develop severe hyperlipidemia due to an accumulation of chylomicrons and Very-Low-Density Lipoprotein (VLDL) and lipoprotein glomerulopathy, making this a model of hyperlipidemic renal injury to study the impact of sex on lesion development." (PMID 37686247, 2023). "In addition, hyperlipidemia is known to blunt the immune response to the periodontopathogen P. gingivalis in apolipoprotein E knockout mice." (PMID 37384642, 2023). "As expected, hyperlipidemia was more common in APOE ε4-carriers (p = 0.009)." (PMID 37400888, 2023). "In the present study, we mainly focused on metabolite Neu5Ac and confirmed that the levels of Neu5Ac in hyperlipidemia patients as well as ApoE-/- mice were both up-regulated and displayed as an important risk factor in circulation for EC injury and AS progression." (PMID 37771765, 2023). "However, it is unclear if p16 activates the NLRP3 inflammsome pathway and aggravates inflammaging.In our study, ApoE−/− and ApoE−/−p16−/− mice were used to establish hyperlipidemia model." (PMID 36457728, 2022). "ApoE−/− mice fed with HFD not only suffer from hyperlipidemia but also induce liver steatosis." (PMID 36498935, 2022). "APOE ε3 is considered a parental form and is related to normal plasma cholesterol levels, while the function of APOE ε2 and APOE ε4 genotypes is altered and related to the occurrence of hyperlipidemia." (PMID 35209166, 2022). "Interestingly, validation in both WT and ApoE−/− mice revealed ApoB reactive memory T-cells are progressively activated in conditions of hyperlipidemia, and that their existence predates the onset of atherosclerotic disease." (PMID 35419441, 2022). "ApoE−/− CON mice exhibited hyperlipidemia and increased oxidative stress, compared to the WT mice." (PMID 34206159, 2021). "Therefore, ApoE−/− mice were used to study the effects of hyperlipidemia on the expression of CCN1 in retinal vascular tissue." (PMID 34458333, 2021). "Indeed, Xbp1 ablation has been reported to ameliorate liver steatosis and injury, as well as hyperlipidemia in ApoE(-/-) mice." (PMID 33467546, 2021).
hyperlipidemia (continued). "Taking together, in hyperlipidemia status, the IL-35–promoted ApoE–/– CCR5+ Tregs exhibit a lower Akt/mTOR activation, suggesting that IL-35 may play a vital role in maintaining a stable Treg immunosuppressive signature in hyperlipidemia." (PMID 34622804, 2021). "ApoE-/- mice, with the background of natural hyperlipidemia, was selected in this study." (PMID 33864447, 2021). "Both hApoE2 and ApoE KO rats exhibited hyperlipidemia when fed with the normal diet." (PMID 34361033, 2021). "Furthermore, the results show that Tregs in different tissues in ApoE–/– responded to hyperlipidemia differentially." (PMID 34622804, 2021). "In addition, hyperlipidemia also increased CD45+ cells (31.6%) in ApoE–/– aortas compared with WT controls (18.8%)." (PMID 34622804, 2021). "To show a definitive role for α9β1 in SMC biology and neointimal hyperplasia in the comorbid condition of hyperlipidemia, we generated SMC-specific α9-deficient mice on apolipoprotein E–deficient (Apoe–/–) background (α9fl/fl SM22αCre+ Apoe–/–; hereafter for simplicity referred to as α9SMC-KO)." (PMID 34027892, 2021). "On the other hand, the transplantation of feces from C57BL/6 mice fed with normal diet to ovariectomized HFD-fed ApoE−/- mice was sufficient to correct the hyperlipidemia and AS damage, and to reverse the characteristics changing of lipid metabolomics in ovariectomized HFD-fed ApoE−/- mice." (PMID 33691599, 2021). "The apoE knockout mouse is a widely used model for the study of human hyperlipidemia." (PMID 33584832, 2021). "Notably, the lipid profile of APOE2-TR mice resembles the small portion of human APOE*ε2 homozygotes who develop hyperlipidemia, raising cautions when interpreting results from studies using APOE2-TR mice." (PMID 33148290, 2020). "These associations validate previously reported relationships between APOE SNPs and hyperlipidemia." (PMID 32711518, 2020). "Importantly, we provide the first direct evidence that JC-5411 has the potential to treat hyperlipidemia observed through animal models including WD induced ApoE−/− mice and hyperlipidemic golden hamsters." (PMID 33442380, 2020). "Thus, we performed this experiment to investigate the effects of EPC treatment on hyperlipidaemia-related kidney disease in an ApoE−/− mouse model." (PMID 32209093, 2020). "Hyperlipidemia, especially an elevated ratio of ApoE/A1 or non-HDL/HDL levels, are known risk factors for ischemic stroke." (PMID 32582015, 2020). "Even when kept on a normal diet, ApoE-/- rabbits develop mild hyperlipidemia." (PMID 32428130, 2020). "On the other hand, other interesting genes, not responsible for FH but associated with hyperlipidemia (such as APOE and LIPA), have been identified." (PMID 33137929, 2020). "In the present study, STZ-induced diabetic ApoE−/− mice displayed severe hyperlipidemia, characterized by elevated serum LDL-c, TC, and TG levels, which were reversed by GBE administration, suggesting that GBE could lower lipid levels in diabetic settings." (PMID 29682154, 2018).
hyperlipidemia (continued). "Among apoE’s newfound athero-protective properties include an ability to control exaggerated hematopoiesis, blood monocyte activation and aortic stiffening in mice with hyperlipidemia." (PMID 29789495, 2018). "Additionally, a previous report has indicated that ApoC1 production drives hyperlipidemia and pathogenesis in the ApoE−/− model, making it a likely candidate for correlation with reduced plaque formation during infection." (PMID 30483256, 2018). "Human hyperlipidemia often results in apoE accumulation in plasma and atheroma." (PMID 29789495, 2018). "Therefore, we concluded that miR-26a overexpression inhibited hyperlipidemia in HFD-treated apoE−/− mice." (PMID 29387339, 2018). "The Lp(a) mice used here were of similar age to the apoE-/- mice used in those studies but the hyperlipidaemia is much milder and the Lp(a) mice were clearly still at a point where they could mount a robust antioxidant response in the liver." (PMID 30596094, 2018). "Interestingly, these serum lipid parameters were unaffected by luseogliflozin administration to NA/STZ-treated ApoE KO mice, although the NA/STZ-induced diabetic state was associated with more severe hyperlipidemia." (PMID 28777298, 2017). "In the current review, we discuss the correlation between apoE structure and its involvement in various pathologies (hyperlipidemia, cardiovascular and neurodegenerative diseases, infections and stress-related dysfunctions), in a view of prospective apoE-based therapeutic strategies." (PMID 28660014, 2017). "In addition, we noted that 542 can reduce serum lipid level in both ApoE−/− mice and WT mice, while AG only showed slightly effects on hyperlipidemia." (PMID 27014908, 2016). "Body weight gain and hyperlipidemia of apoE-/- mice were induced by high-fat diets for 15 weeks." (PMID 25933220, 2015). "Macrophage apoE has been shown to alleviate hyperlipidemia in Apoe−/− mice." (PMID 26695075, 2015). "In this context, ApoE knockout mouse fed a high-fat diet, which displays massive cholesterol accumulation, is a well-accepted model for studying the effects of early onset hyperlipidemia on renal damage." (PMID 24386260, 2013). "While plasma apoE concentrations were not established in this study, it can be speculated that higher levels of apoE in fish oil fed hamsters may partially contribute to the observed hyperlipidaemia." (PMID 18070363, 2007). "Further, the proband's untreated son had combined hyperlipidemia, with approximately equimolar elevations of plasma total cholesterol and triglycerides, which together with an APOE E2/E2 genotype were highly suggestive of type 3 hyperlipoproteinemia (dysbetalipoproteinemia)." (PMID 17883852, 2007). "Moreover, UCAO without L-NAME caused infarction in ~22% C57BL/6 and ~31% ApoE knock-out mice with hyperglycemia/hyperlipidemia, which associated with ~60% greater levels of symmetric dimethylarginine (SDMA, an endogenous NOSi)." (PMID 39744690, 2025). "Hemodynamic characteristics and changes in wall stress or morphology of the aneurysmal aorta might differ in those diseases from the ApoE−/− Ang II mouse model utilized, in which AAA is induced by increased blood pressure levels, hyperlipidemia, and atherosclerotic predisposition." (PMID 37894941, 2023).